INS (insulin)
Diseases named in the same sentence as INS in open-access papers (continued):
Sharing a sentence is not in itself a finding about the gene and the disease.
Hypoglycemia (continued). "Recent evidence has shown that the combination of insulin with GLP1R agonist, provided a similar reduction of HbA1c to a “basal-plus” or a “full basal-bolus” insulin regimen while inferring reduced hypoglycemia and body weight." (PMID 36676765, 2023). "Indeed, evidence suggests that sitagliptin and other DPP-4is are able to reduce daily insulin requirements and improve glucose control without increasing the risk of hypoglycemia or compromising the glucagon counterregulatory response during hypoglycemia in patients with T1D." (PMID 37249465, 2023). "The participants who will receive medication consultations include any participant taking glucose-lowering medications such as insulin or sulfonylureas that may put the participant at risk of hypoglycemia regardless of which diet intervention they are assigned to." (PMID 37475033, 2023). "Previous studies have found that the use of hypoglycemic drugs like sulfonylureas and insulin may cause hypoglycemia during hemodialysis, but the hypoglycemic drugs did not enter the risk prediction model of hypoglycemia during hemodialysis for the patients with DN in this study." (PMID 37833779, 2023). "In addition, by not stimulating insulin secretion, it does not cause hypoglycemia." (PMID 37373620, 2023). "The three groups were followed up for 6 months with an assessment of insulin daily dose (IDD), frequency of hypoglycemia and severe hypoglycemia/week, and HbA1c." (PMID 36800034, 2023). "Furthermore, symptomatic and hormonal counterregulatory responses to hypoglycaemia were compared between icodec and glargine U100 in a subgroup analysis that only included individuals when they actually experienced hypoglycaemia after a double or triple dose of either insulin product." (PMID 37308751, 2023). "Euglycemic DKA patients had milder DKA on presentation based on pH, bicarbonate, and anion gap, were on insulin infusions for shorter amounts of time, had shorter total hospital LOS, and notably had significantly higher rates of hypoglycemia during treatment." (PMID 38165186, 2023). "In two observational studies investigating insulin NPH versus detemir in pregnancies with T2DM or GDM, the rate of hypoglycemia between the two groups was comparable." (PMID 37775682, 2023). "Although SGLT2 inhibitors do not cause hypoglycemia, they can lead to hypoglycemia when the patient is on another agent such as insulin or a sulfonylurea; therefore, decreasing the doses of insulin and/or sulfonylurea could be appropriate when adding SGLT2 inhibitors." (PMID 35054076, 2022). "The primary outcome was the HbA1c level, and secondary outcomes included the body mass index (BMI), total insulin daily dose (TIDD) (unit/kg/d), hypoglycemia events, diabetes ketoacidosis (DKA) events, and gastrointestinal adverse events (GIAEs)." (PMID 35707462, 2022). "Insulin was able to stimulate OXRs, in turn, OXA injection provoked pancreatic stimulation following insulin-induced hypoglycemia, an effect that was blocked using an OXA antagonist." (PMID 36457603, 2022). "The incidence rates of SGLT2i-induced hypoglycemia are similar to current antidiabetic drugs such as MET, glitazones, and DDP-4 inhibitors, and they are substantially lower when compared to insulin or SU." (PMID 35329796, 2022). "VIP-induced glucagon secretion occurs during hypoglycemia, while VIP exerts its role of promoting insulin secretion during hyperglycemia." (PMID 36204104, 2022). "Although insulin treatment reduces fasting plasma glucose (FPG) and HbA1c effectively, it also increases the risks of hypoglycemia and weight gain." (PMID 35097130, 2022). "They proposed that when hypoglycemia is expected, the CGM sensor sends a signal to the pump to cease injecting insulin." (PMID 35862181, 2022). "Hypoglycemia can also result directly from antidiabetic medications (ADM), especially sulfonylureas (SFU) and basal insulin (BI)." (PMID 35114955, 2022).
Hypoglycemia (continued). "Of these 27 patients who successfully switched to a new mode of insulin delivery, 23 (85.2%) saw improvements in their TIR, and 2 more who had been experiencing excess hypoglycemia meaningfully reduced their TBR by more than 2.1% or 30 minutes a day." (PMID 35323114, 2022). "Compared with basal insulin, the patients who use premixed insulin had higher GV, smaller TIR and an increased incidence of hypoglycaemia." (PMID 35574003, 2022). "For example, the combination of basal insulin and glucagon-like peptide 1 receptor agonist (GLP-1 RA) has potent glucose-lowering actions and less weight gain and hypoglycemia compared with intensified insulin regimens." (PMID 36015100, 2022). "Glucose increase is the principal determinant of GLP-1 increase with the consequent stimulation of insulin secretion, the latter balanced by a paradoxical glucagon increase that stimulates EGP to prevent hypoglycaemia." (PMID 33895917, 2022). "Three studies (two RCTs) out of four demonstrated that insulin dosage reduction of between 25 and 40% TDD decreases rates of hypoglycemia for some participants." (PMID 35634376, 2022). "Therefore, new insulin pumps could reduce hypoglycaemia onset and severity." (PMID 36422210, 2022). "Though more intensified insulin regimens have a potential benefit in the lowering of blood glucose and delaying the onset of complications, they may also have negative possible effects like higher risk of weight gain, hypoglycemia and hyperinsulinemia." (PMID 36149907, 2022). "This can lead to overdoses of insulin when a shorter DIA value than actual is used in safety schemes based on the IOB, triggering episodes of hypoglycemia since the algorithm assumes there is less IOB than there actually is." (PMID 35265035, 2022). "While normal neuronal architecture was observed in 35% of cases, this could be indicative of a short survival period post-insulin administration, and thus, the presence or absence of neuronal pathology cannot be considered diagnostic of fatal hypoglycaemia without a detailed timeline of events." (PMID 35943711, 2022). "In summary, compared with basal insulin, the patients who currently use premixed insulin had more severe GV, a smaller TIR and a higher incidence of hypoglycaemia." (PMID 35574003, 2022). "This included a collection of blood in the critical period (of hypoglycemia) for cortisol, free thyroxine (FT4), thyroid-stimulating hormone (TSH), growth hormone (GH), insulin, and C-peptide." (PMID 35495001, 2022). "Most people are familiar with the central interactions between insulin and the HPA axis during hypoglycemia." (PMID 35897752, 2022). "According to a survey of treatment-related severe hypoglycemia conducted by the JDS, more than 90% of Japanese patients with T2DM who experienced severe hypoglycemia were being treated with insulin and/or sulfonylureas." (PMID 35908248, 2022). "Children with post-prandial hypoglycemia after Nissen fundoplication exhibit higher GLP-1 and insulin plasma concentrations, and lower plasma glucose nadir in response to an oral glucose tolerance test than controls." (PMID 35399928, 2022). "I have trialled different long-acting insulin doses on the morning of the event, recognising that I need some background insulin, but not so much that it will cause hypoglycaemia when I start exercising, as I swim most days, I find that this dose is the same whether I have an event or training." (PMID 36425473, 2022). "Insulin supplementation of STZ-diabetic, keto diet-fed animals proved to be unfeasible due to severe hypoglycemia experienced by all animals." (PMID 36676967, 2022). "introduced a new insulin sensitivity adaptation (ISA) algorithm and adaptive learning postprandial hypoglycemia prevention (ALPHA) algorithm." (PMID 36411933, 2022).
Hypoglycemia (continued). "The development of sensor-augmented pump (SAP) therapy, which is the combination of continuous subcutaneous insulin infusion (CSII) and continuous glucose monitoring (CGM), has permitted reductions in DKA and severe hypoglycemia." (PMID 35498423, 2022). "This could explain why alginate DCs that did not produce physiological insulin response in vitro caused hypoglycemia in the transplanted mice in vivo: prolonged exposure to high local glucose concentrations exhausts the insulin-producing β cells and shuts down the glucagon-producing α cells." (PMID 35651551, 2022). "Therefore, this study suggests that the administration of imipramine when severe hypoglycemia occurs in diabetic patients prescribed insulin could be a potentially promising therapeutic approach to prevent hippocampal neuronal death and cognitive deficit during hypoglycemia/glucose reperfusion." (PMID 35203316, 2022). "Out of the three participants who had nocturnal hypoglycemia the night following L-ACT, only one reported administrating an insulin bolus correction in the evening." (PMID 36237197, 2022). "Among 45 neonates with hypoglycaemia, 12 were born to mothers with GDM who received insulin therapy during pregnancy, and 24 were born to mothers with GDM whose GDM was diagnosed before 24 gestational weeks." (PMID 34267729, 2021). "While on insulin treatment, there was one case of DKA and one case with convulsion due to severe hypoglycemia." (PMID 34566892, 2021). "Besides, findings were also observed that ST Breaks times could significantly improve the body's glucose metabolism with no increase in total energy intake among overweight and obese children, and positively reduce postprandial hypoglycemia and insulin responses among adults." (PMID 35047464, 2021). "However, insulin secretion is already stimulated independently of glycemia in patients treated with sulfonylureas, and the addition of a glucose execration effect may result in an increase in the incidence of hypoglycemia." (PMID 34744998, 2021). "LPS challenge induced hypoglycemia and acute cognitive impairment in mice with brain disease (ME7 prion infection), which was mitigated by glucose and mimicked by insulin." (PMID 34795562, 2021). "Moreover, it has been suggested that closed-loop and sensor-augmented pump insulin delivery could be efficient to lower blood glucose levels without increasing the risk of severe hypoglycemia in pregnant women." (PMID 35069449, 2021). "In the CLAMP, C-peptide decreased from start of hypoglycaemia until end of study for both groups and likewise, in the BOLUS, from t15 to t60, indicating suppression of endogenous insulin production." (PMID 33727615, 2021). "However, youth in the insulin pump group reported fewer hypoglycemia episodes (i.e., “1-3 times/year” and “4-12 times/year”) than those who used injections (who more frequently reported having hypoglycemia “more than once/week” and high “more than once/month”)." (PMID 34557162, 2021). "Subjects developing postprandial hypoglycemia have been shown to have higher postprandial bile acids levels coinciding with augmented GLP-1 and insulin responses during a mixed meal." (PMID 34084153, 2021). "Insulin therapy can cause weight gain due to an over-replacement of insulin which produces a general anabolic effect, decreased energy expenditure, greater carbohydrate intake in response to the perceived risk of hypoglycaemia and the non-physiological mode administrating insulin." (PMID 34684518, 2021). "Hypoglycemia in LQP, hypoinsulinemia and lower HOMA-IR in LQP and LP offspring suggests that these animals had enhanced insulin sensitivity." (PMID 34836384, 2021). "In conclusion, the present study provides evidence that metformin is as effective as insulin for glycemic control in GDM and is superior with respect to the prevention of adverse neonatal outcomes, such as neonatal hypoglycemia, macrosomia, and NICU admission." (PMID 34641848, 2021).
Hypoglycemia (continued). "Although there was a pattern of increasing sulfonylurea and/or insulin deintensification over a 10-year period, low overall rates of deintensification suggest that real-world practice may lag behind evidence that positions severe hypoglycemia as a major health and safety concern among older adults." (PMID 34726745, 2021). "However, there must be other unknown mechanisms underlying the effect of insulin treatment on the outcomes of COVID-19, as the effect still remains in patients without hypoglycemia during hospitalization." (PMID 34367067, 2021). "During insulin treatment, patient 2 was admitted to the hospital twice (due to DKA and convulsion due to severe hypoglycemia)." (PMID 34566892, 2021). "Problematic nocturnal hypoglycemia (often occurring in the setting of pregnancy, steroid therapy, or liver disease) could also be a reason to consider whether continuing to increase the basal insulin dose is warranted or whether other therapeutic approaches are needed." (PMID 34165382, 2021). "However, the lack of impairment in insulin-induced hypoglycemia in mice deficient in mGluR5 is in contrast to the previous investigation in which inhibition of glutamate release by SF1 neurons impaired the CRR to hypoglycemia." (PMID 34201257, 2021). "Secondary outcomes included frequency of FSBG by insulin status, distribution of FSBG checks by time of day, and hypoglycemia rates." (PMID 34758807, 2021). "This meta-analysis concluded similar efficacy of currently available long-acting insulin (insulin degludec and glargine) in T2DM patients in the Asian region, with lower hypoglycemia episodes with insulin glargine." (PMID 34345540, 2021). "It would be very interesting to follow a cohort of CSH RNAi offspring into adulthood to examine adult glucose homeostasis and insulin sensitivity, as CSH RNAi results in both hypoglycemia and likely hypoinsulinemia." (PMID 34360913, 2021). "Significant differences were observed in glycemic goal (35.53% SH versus 25.80% HH-DBT, p < 0.01), insulin use rate (26.66% SH versus 46.58% HH-DBT, p < 0.01), and severe hypoglycemia rate (1.32% SH versus 1.74% HH-DBT, p < 0.01)." (PMID 34852895, 2021). "Male and female rats were infused icv with the aromatase enzyme inhibitor letrozole (Lz) prior to sc vehicle (V) or insulin (INS) injection to investigate the impact of neuroestradiol on rostral VMN AMPK and pAMPK protein expression during eu- or hypoglycemia." (PMID 33490375, 2021). "Thus, the add-on of GLP1-RA and/or SGLT2i to insulin therapy can reduce the dose of insulin, or even allow for its withdrawal, as well as achieve a good glycaemic control with no weight gain and reduced risk of hypoglycaemia, with the added advantage of cardiorenal benefits." (PMID 34070103, 2021). "There were also concomitant decreases in circulating insulin and increases in glucagon, typical of the counter-regulatory response (CRR) to hypoglycemia." (PMID 34265067, 2021). "In another prior study, patients seem to do better with an insulin pump after one year of use, with improved glycemic control, and decreased incidence of DKA and hypoglycemia." (PMID 33668749, 2021). "Use of CGM, with or without an insulin pump, has abrogated much of the problematic hyper- and hypoglycemia in both MDI and insulin pump users, and this is further improved by the use of insulin pumps with automated insulin delivery." (PMID 34077674, 2021). "Only three of these reviews mentioned cases of hypoglycaemia, including only one reported case of a hypoglycaemic seizure in a clinical trial of cinnamon given to adolescent T1DM patients on insulin." (PMID 34899340, 2021). "Pregnant women with detected C-peptide had better-regulated glycemia, fewer hypoglycemia events according to CGM, reduced total insulin dose, and lower incidence of macrosomia." (PMID 34959363, 2021).
Hypoglycemia (continued). "However, the best scenario would be to alert the patient of the risk of post-prandial hypoglycemia at the time of meal bolus, so that the patient could decide to reduce the meal insulin bolus amount, thus avoiding hypoglycemia and the need to consume extra carbs." (PMID 32664432, 2020). "Inhibition of potassium-ATP(K-ATP) channels in pancreatic B-cells, with consequent insulin secretion increase, and inhibition of antidiabetic CYP metabolism by fluoroquinolones have been postulated as mechanisms of hypoglycemia." (PMID 33024058, 2020). "As seen in previous studies, participants in our study reduced the basal insulin rate for CSII by almost 50% at the competition day, which was sufficient to protect against hypoglycaemia." (PMID 32915897, 2020). "This uncontrolled release of insulin in CHI can lead to frequent and severe bouts of hypoglycemia, which in turn can have severe and lasting consequences on central nervous system (CNS) function and neurodevelopment in young children." (PMID 33013678, 2020). "In conclusion, we found that the insulin regimen used, admission with an infection, ICU admission, lower BMI, and nutritional therapy were independent predictive factors of hypoglycemia among hospitalized patients with T2DM." (PMID 32133264, 2020). "The incidence of hypoglycemia remains relatively high with a standard IDT protocol of 25 g of glucose and 10 U of insulin." (PMID 33328554, 2020). "However, it is unclear if achieving this via restricted carbohydrate feeding, rather than by administering more insulin or by some other means, may compromise endurance performance and/or increase hypoglycaemia or ketoacidosis risk." (PMID 32533229, 2020). "We should keep in mind that even a long-inactive SFT can undergo transformation to produce big IGF-2, which then acts on both insulin and IGF-1 receptors, possibly leading to both hypoglycemia and the development/growth of another tumor, respectively." (PMID 32993631, 2020). "In contrast, over-dosing with human insulin (60% of the OI320 maintenance dose) quickly affects both glucose Ra and Rd, leading to acute hypoglycaemia and requiring intervention with glucose infusion to prevent plasma glucose levels from dropping below 2.5 mM." (PMID 32719315, 2020). "In a recent outpatient study, combination therapy of basal insulin and a GLP‐1RA reduced hypoglycemia and suppressed GV compared with other treatment regimens, such as BBT28." (PMID 31168938, 2020). "To induce adequate hypoglycemia with a single dose of insulin and avoid repeated doses in ITT, we evaluated our personalized calculation method of insulin dosage in this study." (PMID 32328036, 2020). "Continuous subcutaneous insulin infusion (CSII) therapy, CGM, and a combination of both (with the use of a sensor augmented pump (SAP)) have significantly reduced the frequency of hypoglycemia (including NH)." (PMID 32204318, 2020). "NICTH was suspected due to fasting hypoglycemia, low IGF-I, suppression of insulin secretion and a large tumor." (PMID 32393233, 2020). "Thus, the question arises whether elevated gluconeogenic pathways in INT-offspring may be part of a compensatory mechanism to avoid hypoglycemia during a phase of increased insulin sensitivity at P21 and further research is needed to clarify the effects of ME on offspring hepatic gluconeogenesis." (PMID 32963289, 2020). "Previous studies demonstrate that patients with insulin-treated T2DM, but low postprandial C-peptide levels, have markedly increased glucose variability and incidence of hypoglycemia and hyperglycemia compared with those who retained C-peptide." (PMID 33023555, 2020). "Re-suspending cloudy insulin: no patients in this study ́s sample adequately follows the recommendations about this crucial step of reconstitution for nocturnal hypoglycemia (NPH) and premix insulin." (PMID 33193981, 2020).